DDX23 (DEAD-box helicase 23)
Description:
Involved in pre-mRNA splicing and its phosphorylated form (by SRPK2) is required for spliceosomal B complex formation. Independently of its spliceosome formation function, required for the suppression of incorrect R-loops formed during transcription; R-loops are composed of a DNA:RNA hybrid and the associated non-template single-stranded DNA.
Synonyms: Prp28; U5-100KD; PRPF28; SNRNP100; U5-100K
Tractability: Small molecule: a structure with a bound ligand is known. PROTAC: UniProt records ubiquitination sites on it; ubiquitination databases record sites on it; its protein half-life has been measured.
Gene: Protein-coding gene on chromosome 12 (48,829,756 to 48,852,842, reverse strand). Ensembl gene ENSG00000174243.
Subcellular location: Nucleus; Chromosome
Subcellular location (Human Protein Atlas): Nucleoli; Nucleoplasm
Pathways (Reactome):
Metabolism of RNA: mRNA Splicing - Major Pathway; mRNA Splicing - Minor Pathway
Disease: Dengue Virus-Host Interactions
Gene Ontology:
Molecular function: helicase activity; protein binding; RNA binding; RNA helicase activity; ATP binding; ATP hydrolysis activity; nucleic acid binding
Biological process: R-loop processing; cis assembly of pre-catalytic spliceosome; mRNA splicing, via spliceosome; RNA splicing; RNA splicing, via transesterification reactions; spliceosomal snRNP assembly; spliceosomal tri-snRNP complex assembly; spliceosome conformational change to release U4 (or U4atac) and U1 (or U11)
Cellular component: catalytic step 2 spliceosome; chromatin; chromosome; extracellular exosome; nucleolus; nucleoplasm; nucleus; precatalytic spliceosome; spliceosomal complex; U12-type precatalytic spliceosome; U4/U6 x U5 tri-snRNP complex; U5 snRNP; U4atac/U6atac x U5 tri-snRNP complex
Genetic constraint (gnomAD): Loss-of-function variants: 33 observed, 107.23 expected, observed/expected ratio (o/e) 0.31, 90% interval 0.23 to 0.41. The upper end of that interval is the gene's LOEUF score, 0.41, which puts it in group 1 of 6, group 1 being the genes least tolerant of losing a copy. Missense variants: 549 observed, 1,130 expected, observed/expected ratio (o/e) 0.49, 90% interval 0.45 to 0.52. Synonymous variants: 352 observed, 397.71 expected, observed/expected ratio (o/e) 0.89, 90% interval 0.81 to 0.97.
Gene-disease validity (ClinGen):
ClinGen rates the evidence that DDX23 causes each of these diseases.
complex neurodevelopmental disorder (autosomal dominant): Moderate. A disorder that involves more than one phenotype associated with the central nervous system, including but not limited to intellectual disability, autism, and seizures (epilepsy).
Homologues: Orthologues: chimpanzee DDX23 (99% identical), macaque DDX23 (99% identical), dog DDX23 (99% identical), pig DDX23 (99% identical), guinea pig DDX23 (99% identical), rabbit DDX23 (99% identical), mouse Ddx23 (99% identical), rat Ddx23 (99% identical), tropical clawed frog ddx23 (91% identical), zebrafish ddx23 (85% identical), Drosophila melanogaster CG10333 (66% identical), Caenorhabditis elegans ddx-23 (54% identical). Paralogues in human: DDX46 (26% identical), DDX59 (23% identical), DDX43 (22% identical), DDX3X (22% identical), DDX3Y (22% identical), DDX42 (22% identical), DDX41 (22% identical), DDX5 (21% identical), DDX17 (20% identical), DDX53 (20% identical), DDX4 (20% identical), DDX27 (19% identical), and 26 more.
Diseases named in the same sentence as DDX23 in open-access papers:
DDX23 is named in the same sentence as 22 diseases in open-access papers, as found by Europe PMC text mining. Sharing a sentence is not in itself a finding about the gene and the disease. The quoted sentences say what the papers report.
glioma (5 papers, 2016 to 2024). A benign or malignant brain and spinal cord tumor that arises from glial cells (astrocytes, oligodendrocytes, ependymal cells). "The expression of DDX23 is enhanced in glioma tissues, and this is associated with poor survival of glioma patients." (PMID 36761420, 2022). "DDX23 expression was elevated in glioma patients and it had been strongly linked to the poor prognosis of glioma." (PMID 34966670, 2021). "Abnormal DDX23 expression has been implicated in glioma progression and poor survival." (PMID 34966670, 2021). "DDX23 was previously reported to promote the invasion and proliferation of glioma cells." (PMID 34966670, 2021). "DDX23 promotes the proliferation of glioma cells by modulating miR-21 biogenesis." (PMID 27835882, 2016). "Thus, unlike other U5 proteins associated with cancer, the key role of DDX23 upregulation in glioma progression does not appear to stem from specific alterations in pre-mRNA splicing, but rather through additional functions of the protein, in this case microRNA processing." (PMID 33584830, 2021). "Finally, it is interesting that the link between DDX23 and glioma progression stems from a non-spliceosomal role of the protein." (PMID 33584830, 2021).
hepatocellular carcinoma (2 papers, 2021 to 2023). A malignant tumor that arises from hepatocytes. "DDX23 was also upregulated in hepatocellular carcinoma and correlated with advanced clinicopathological stages." (PMID 34966670, 2021). "In hepatocellular carcinoma, SDC4/DDX23 axis played a crucial role in driving cell proliferation and migration." (PMID 34966670, 2021). "DDX23, as a substrate protein, was reported to interact with SDC4 with the aid of bufalin, a small molecule anticancer drug, to induce inactivated matrix metalloproteinases and elevated p38/JNK MAPKs phosphorylation in hepatocellular carcinoma." (PMID 36977668, 2023).
ovarian carcinoma (2 papers, 2021 to 2024). A malignant neoplasm originating from the surface ovarian epithelium. "In this study, DDX23 was first identified as a key DEAD-box RNA helicase in ovarian cancer, and its overexpression was associated with poor clinical outcomes." (PMID 34966670, 2021). "The expression of associated cell cycle regulators also changed in DDX23-depleted ovarian cancer cells." (PMID 34966670, 2021). "In summary, our study was the first to demonstrate that DDX23 was upregulated in ovarian cancer and was associated with poor clinical outcomes." (PMID 34966670, 2021). "Taken together, these results strongly indicated that DDX23 was highly expressed in ovarian cancer tissues and was significantly associated with poor prognosis in ovarian cancer patients." (PMID 34966670, 2021). "DDX23 expression was an independent high-risk factor closely associated with the OS of ovarian cancer patients." (PMID 34966670, 2021). "We determined that DDX23 was upregulated in ovarian cancer and its high expression predicted poor prognosis." (PMID 34966670, 2021). "Taken together, this study demonstrates the clinical and biological significance of DDX23 in ovarian cancer and provides a new target for tumor precision therapy." (PMID 34966670, 2021). "In our study, DDX23 silencing significantly impeded the proliferation of ovarian cancer cells through G1 phase arrest." (PMID 34966670, 2021). "Compared with FT specimens, IHC staining revealed significantly higher DDX23 expression in ovarian cancer specimens (P < 0.01)." (PMID 34966670, 2021). "To further explore the role of DDX23 in ovarian cancer, we performed relevant functional experiments in vitro and in vivo." (PMID 34966670, 2021). "We further analyzed data of TCGA cohort and found a significantly higher mRNA level of DDX23 in ovarian cancer samples (n = 585) compared with normal ovary samples (n = 8) (P < 0.01)." (PMID 34966670, 2021). "In wound healing assays, at 12h post-scratch, ovarian cancer cells with DDX23 knockdown migrated less than NC group in A2780, SKOV3, and HEY cells (all P < 0.0001)." (PMID 34966670, 2021). "Co-expression analysis revealed that the mRNA expression of E2F1 and DDX23 were positively correlated in ovarian cancer (Spearman’s correlation = 0.38, P = 1.34e-7)." (PMID 34966670, 2021). "Biological process analysis showed that DDX23 was involved in mRNA processing, which confirmed the splicing-related functions of DDX23 in ovarian cancer." (PMID 34966670, 2021). "Altogether, these results indicated that FOXM1 was a key executor in DDX23-induced malignant phenotype of ovarian cancer." (PMID 34966670, 2021). "Mechanistically, transcriptomic analysis showed that DDX23 was involved in mRNA processing in ovarian cancer cells." (PMID 34966670, 2021). "Given that DDX23 was upregulated in ovarian cancer, we then explored the role of DDX23 in the proliferation of ovarian cancer cells." (PMID 34966670, 2021). "Overall, these data suggested that DDX23 was required for ovarian cancer cell proliferation, and DDX23 knockdown inhibited cell proliferation through G1 phase arrest." (PMID 34966670, 2021). "In this study, we identified DEAD-box helicase 23 (DDX23) as a key DEAD-box RNA helicase in ovarian cancer using bioinformatics methods." (PMID 34966670, 2021). "Our study also revealed that DDX23 was transcriptionally activated by E2F1, contributing to the elevated expression of DDX23 in ovarian cancer." (PMID 34966670, 2021). "Specifically, DDX23 expression was found to be elevated in multiple tumor types including ovarian cancer (P < 0.0001)." (PMID 34966670, 2021). "Rescue assays indicated that FOXM1 was a key executor in DDX23-induced malignant phenotype of ovarian cancer." (PMID 34966670, 2021). "Since the effect of DDX23 on the progression of ovarian cancer was determined in vitro, we further constructed nude mouse xenograft models to explore the role of DDX23 in ovarian cancer tumorigenesis in vivo." (PMID 34966670, 2021).
ovarian carcinoma (continued). "In summary, these data indicated that DDX23 was a direct transcriptional target of E2F1 in ovarian cancer cells." (PMID 34966670, 2021). "In our study, we first determined that DDX23 was overexpressed and significantly correlated with poor clinical outcomes in ovarian cancer." (PMID 34966670, 2021). "High expression of DDX23 was involved in the malignant proliferation and aggressiveness of ovarian cancer cells by regulating FOXM1 mRNA processing." (PMID 34966670, 2021). "Results showed that 14.5% (10/69) FT samples had high DDX23 expression, whereas 33.9% (42/124) ovarian cancer samples belonged to high DDX23 group." (PMID 34966670, 2021). "We subsequently confirmed that E2F1 could bind to the DDX23 promoter region directly and regulate DDX23 transcription in ovarian cancer cells." (PMID 34966670, 2021). "Furthermore, we confirmed that DDX23 was transcriptionally activated by the transcription factor (TF) E2F1 in ovarian cancer using luciferase reporter assays and chromatin immunoprecipitation (ChIP) assays." (PMID 34966670, 2021). "To determine whether DDX23 contribute to overall FOXM1 function, we performed rescue experiments by co-transfecting the ovarian cancer cells with DDX23 siRNA and FOXM1 plasmid, and examined the cell proliferation and migration." (PMID 34966670, 2021). "Meanwhile, our study also investigated the DDX23 promoter region to predict potential TFs that might regulate the DDX23 upregulation observed in ovarian cancer." (PMID 34966670, 2021). "Cell cycle analysis revealed that compared to NC group, DDX23 silencing could increase the percentage of cells in the G1 phase while decreasing the percentage of cells in S phase in three ovarian cancer cell lines." (PMID 34966670, 2021). "FOXM1 was a key executor in DDX23-induced malignant phenotype of ovarian cancer." (PMID 34966670, 2021). "These experimental results collectively suggested that DDX23 could promote the migration and invasion ability of ovarian cancer cells." (PMID 34966670, 2021). "Transcriptional activation of DDX23 by E2F1 in turn up-regulates DDX23 in ovarian cancer." (PMID 34966670, 2021). "Similarly, we detected the DDX23 mRNA expression in our cohort by qRT-PCR and found that DDX23 had higher expression in ovarian cancer samples (n = 46) than in FT specimens (n = 29) (P < 0.001)." (PMID 34966670, 2021). "In conclusion, our study demonstrates that high DDX23 expression is involved in malignant behavior of ovarian cancer and DDX23 may become a potential target for precision therapy of ovarian cancer." (PMID 34966670, 2021). "However, the specific role of DDX23 in ovarian cancer is less studied." (PMID 34966670, 2021). "Moreover, DDX23 was transcriptionally activated by the E2F1 in ovarian cancer." (PMID 34966670, 2021). "Because of the relative low expression of FOXM1A and FOXM1B in ovarian cancer cells, the FOXM1C expression presented the most significantly decrease after DDX23 knockdown." (PMID 34966670, 2021). "DDX23 silencing reduced the production of FOXM1C, the major oncogenic transcript of FOXM1 in ovarian cancer, thereby decreasing the FOXM1 protein expression and attenuating the malignant progression of ovarian cancer." (PMID 34966670, 2021). "To determine whether E2F1 was involved in the regulation of DDX23 transcription, we first detected the expression of DDX23 in E2F1 knockdown and control ovarian cancer cells." (PMID 34966670, 2021). "However, the function mechanism of splicing factor DDX23 in ovarian cancer has not been elucidated." (PMID 34966670, 2021).
viral infection (2 papers, 2016 to 2019). "Given that DDX23 is a known component of the cellular mRNA splicing machinery, we further explored whether DDX23 influences the alternative splicing of known antiviral factors during viral infection." (PMID 31620127, 2019). "NS5 alone or in the context of viral infection binds to CD2BP2 and DDX23, core components of U5 snRNP, and incorporates in active spliceosomes." (PMID 27575636, 2016). "In particular, we show that NS5 alone, or in the context of viral infection, interacts with core components of the U5 snRNP particle, CD2BP2 and DDX23, alters the inclusion/exclusion ratio of alternative splicing events, and changes mRNA isoform abundance of known antiviral factors." (PMID 27575636, 2016).
adenoid cystic carcinoma (1 paper, 2021). A malignant tumor arising from the epithelial cells. "DDX23 mutations and homozygous deletions have been identified in several different cancers, including adenoid cystic carcinoma (ACC), implicating DDX23 loss as a potential source of genomic instability which may have an important role in cancer development." (PMID 33584830, 2021).
glioblastoma (1 paper, 2024). The most malignant astrocytic tumor (WHO grade IV). "DDX23 can promote cell proliferation and invasive features in glioblastoma by promoting oncogenic miR-21 maturation." (PMID 38689093, 2024). "The role of DDX23 in pri-miR-21 processing is primarily mediated by its intrinsic helicase activity, and the inhibition of its helicase activity for glioblastoma treatment was experimentally demonstrated by using ivermectin, a viral helicase inhibitor." (PMID 38689093, 2024).
myelodysplastic syndrome (1 paper, 2023). A clonal hematopoietic disorder characterized by dysplasia and ineffective hematopoiesis in one or more of the hematopoietic cell lines. "The pharmacological restoration of DDX23 might be a potential therapeutic approach for myelodysplastic syndrome." (PMID 36977668, 2023). "In addition, DDX23 was suspected to be involved in myelodysplastic syndrome." (PMID 36977668, 2023).
pancreatic cancer (1 paper, 2023). "To further illuminate the role of DDX23 in METTL3-induced pancreatic cancer progression, we overexpressed DDX23 in PDAC cells depleted of METTL3." (PMID 36977668, 2023). "In line with this, we found the significant upregulation of DDX23 in pancreatic cancer cell lines compared with HPDE6C7 cell line." (PMID 36977668, 2023). "Our study thus presented DDX23 to be a charming therapeutic target for pancreatic cancer drug development." (PMID 36977668, 2023). "An identified downstream target of METTL3, DDX23 mRNA, was discovered to be upregulated in pancreatic cancer and predict poor survival, as well as positively correlated with PI3K/Akt pathway." (PMID 36977668, 2023). "We subsequently studied how DDX23 affected GEM resistance of pancreatic cancer in a METTL3-dependent manner." (PMID 36977668, 2023). "Based on the findings in our study, we concluded that METTL3 regulated pancreatic cancer phenotypes by modifying its direct target DDX23 mRNA, thus PI3K/Akt signaling." (PMID 36977668, 2023). "The knockdown of METTL3, an m6A methyltransferase, suppressed pancreatic cancer malignancy and gemcitabine resistance by regulating its direct target DDX23 mRNA, thus PI3K/Akt signaling." (PMID 36977668, 2023). "In summary, DDX23 knockdown could significantly suppress the malignant phenotypes of pancreatic cancer cells, in vivo tumor growth as well as lung metastasis in synergy with GEM treatment potentially by regulating PI3K/Akt signaling." (PMID 36977668, 2023). "Additionally, DDX23 silence resulted in the suppression of pancreatic cancer cell malignancy and PIAK/Akt signaling inactivation." (PMID 36977668, 2023). "We herein, for the first time identified DDX23 to be a direct target of METTL3 and an oncogene in pancreatic cancer." (PMID 36977668, 2023). "This study found the significantly upregulated METTL3 in pancreatic cancer, and METTL3 direct target DDX23 mRNA and promotes its translation in a YTHDF1-dependent pathway." (PMID 36977668, 2023).
rhabdomyosarcoma (1 paper, 2024). A rare aggressive malignant mesenchymal neoplasm arising from skeletal muscle. "It is intriguing to speculate whether DDX23 was associated with both BPP and rhabdomyosarcoma in the young female FINLIS18-3 in this study." (PMID 38712318, 2024).
infection (9 papers, 2015 to 2022). The state of being infected such as from the introduction of a foreign agent such as serum, vaccine, antigenic substance or organism. "This RNA-dependent RNA polymerase (RdRp) interacts with CD2BP2 and DDX23 from the U5 snRNP, allowing modulation of cellular AS during infection benefiting the replication of Dengue virus." (PMID 35489070, 2022). "We also measured the DDX23 mRNA levels during infection, which increased as infection progressed, although this did not occur in the mock-infected cells." (PMID 33255534, 2020). "A recent study found that DDX23 is antiviral against dengue virus, and dengue virus NS5 interacts with DDX23 to facilitate infection via modulation of spliceosome activity." (PMID 33109765, 2020). "First, DDX23 knockdown ovarian cell lines were established by lentiviral infection." (PMID 34966670, 2021). "PK-15 cells were infected with FMDV serotype O strain O/BY/CHA/2010 (GenBank accession number JN998085.1) at the multiplicity of infection (MOI) of 0.5, and the expression of DDX23 protein was measured." (PMID 33255534, 2020). "Similarly, three helicase members, DDX6, DDX17, and DDX23 were shown to restrict the replication of RVFV in Drosophila, in which DDX17 binds the essential stem loop in bunya viral RNA to combat infection." (PMID 31620127, 2019). "How DDX23 controls viral infection in amphioxus is unclear, and whether DDX23 binding directly to viral RNA also impacts infection has not been explored." (PMID 32033386, 2020). "In contrast, no significant changes were observed for CD2BP2, DDX23, EFTUD2, SNRNP40 (U5 snRNP components) or SF3A2 (U2 snRNP component) levels up to 48 hours of infection as compared with those in uninfected cells." (PMID 27575636, 2016).